ALKBH7 (alkB homolog 7, RNA demethylase)
Description:
RNA demethylase that demethylates N(2)-dimethylguanosine and N(1)-methyladenosine within mitochondrial pre-tRNA regions. This demethylation activity plays a crucial role in regulating the processing of nascent polycistronic mitochondrial RNA, thereby influencing mitochondrial gene expression and overall mitochondrial activity. In response to extensive DNA damage is required for programmed necrosis induced by alkylation and oxidation. Acts by triggering the collapse of mitochondrial membrane potential and loss of mitochondrial function that leads to energy depletion and cell death. Involved in fatty acid metabolism (By similarity).
Synonyms: ABH7; SPATA11; MGC10974; UNQ6002
Tractability: Small molecule: a structure with a bound ligand is known. PROTAC: its protein half-life has been measured.
Gene: Protein-coding gene on chromosome 19 (6,372,763 to 6,375,250, forward strand). Ensembl gene ENSG00000125652.
Subcellular location: Mitochondrion matrix
Subcellular location (Human Protein Atlas): Mitochondria
Gene Ontology:
Molecular function: oxidative RNA demethylase activity; protein binding; tRNA demethylase activity; 2-oxoglutarate-dependent dioxygenase activity
Biological process: DNA damage response; oxidative RNA demethylation; regulation of mitochondrial membrane permeability involved in programmed necrotic cell death; fatty acid metabolic process; regulation of lipid storage
Cellular component: mitochondrial matrix; mitochondrion
Genetic constraint (gnomAD): Loss-of-function variants: 23 observed, 19.31 expected, observed/expected ratio (o/e) 1.19, 90% interval 0.86 to 1.67. The upper end of that interval is the gene's LOEUF score, 1.67, which puts it in group 6 of 6, group 1 being the genes least tolerant of losing a copy. Missense variants: 354 observed, 296.59 expected, observed/expected ratio (o/e) 1.19, 90% interval 1.09 to 1.3. Synonymous variants: 147 observed, 131.26 expected, observed/expected ratio (o/e) 1.12, 90% interval 0.98 to 1.28.
Homologues: Orthologues: chimpanzee ALKBH7 (100% identical), macaque ALKBH7 (98% identical), dog ALKBH7 (94% identical), pig ALKBH7 (92% identical), rabbit ALKBH7 (88% identical), guinea pig ALKBH7 (85% identical), rat Alkbh7 (82% identical), mouse Alkbh7 (82% identical), tropical clawed frog alkbh7 (53% identical), zebrafish alkbh7 (50% identical), Drosophila melanogaster CG14130 (42% identical), Caenorhabditis elegans alkb-7 (36% identical).
Diseases named in the same sentence as ALKBH7 in open-access papers:
ALKBH7 is named in the same sentence as 22 diseases in open-access papers, as found by Europe PMC text mining. Sharing a sentence is not in itself a finding about the gene and the disease. The quoted sentences say what the papers report.
breast carcinoma (6 papers, 2022 to 2025). "Next, we analyzed the correlation between clinical characteristics and ALKBH7 expression in breast cancer patients and found that higher expression of ALKBH7 was related to higher age, later T stage, ER-positive, PR-positive, and post-menopause." (PMID 35980268, 2022). "This is our next step to conduct the cell biology experiments and clinical verification, especially to investigate the role of ALKBH7 in breast cancer." (PMID 35980268, 2022). "As one of α-ketoglutarate-dependent dioxygenases, ALKBH7 expression was positively associated with D-2-hydroxyglutarate dehydrogenase(D2HGDH) as Gene expression profile data and later is considered a potential prognostic marker in breast cancer." (PMID 35980268, 2022). "In conclusion, our findings may provide novel insights into ALKBH-targeted therapy for breast cancer patients, and ALKBH7 may be a potential prognostic biomarker." (PMID 35980268, 2022). "Moreover, we further found that there was strong correlation between ALKBH7 and higher age, later T stage, ER/PR positive and post-menopause of breast cancer patients, and patients with higher ALKBH7 expression had shorter overall survival (OS) and post progression survival (PPS)." (PMID 35980268, 2022). "In addition, higher ALKBH7 expression was likely to relate to the poor prognosis for patients with breast cancer and might be a potential breast cancer biomarker and possible therapeutic target in the future." (PMID 35980268, 2022). "As the data shown, the OS of breast cancer patient was significant difference when gene expression was changed in ALKBH3 (p=0.00063), ALKBH4 (p=0.013), ALKBH7 (p=0.0025), ALKBH8 (p=0.00013) and FTO (p=0.045)." (PMID 35980268, 2022). "With compared the expression of ALKBH family members in breast cancer and normal samples, the up-regulation was ALKBH1, ALKBH2, ALKBH4, ALKBH6, ALKBH7, and others such as ALKBH3, ALKBH8, FTO was down-regulation." (PMID 35980268, 2022). "The evidence of ALKBH7 and NLRP3 co-expression proposes a novel functional link between these molecules, potentially representing a dual-function mechanism that integrates metabolic adaptation and immune signaling in breast cancer." (PMID 41373809, 2025). "Moreover, in the case of control samples, we found overexpression of the proteins: PRDX2, PRDX5 and AIFM1 involved in ROS; TUSC2 in PMM; ALKBH7, RHOT1, SAMM50, IMMT and HSPA9 in the MMO; and FUNDC2 in MIT compared to luminal A and basal-like breast cancer tumors." (PMID 35327574, 2022). "In addition, there were significant differences in the expression of ALKBH7 among different immune and molecular subtypes of breast cancer (BRCA), prostate adenocarcinoma (PRAD), and uterine corpus endometrial carcinoma (UCEC), suggesting that ALKBH7 may play a role in tumor growth and development." (PMID 37654657, 2023).
Obesity (5 papers, 2017 to 2023). Accumulation of substantial excess body fat. "A previous study reported that the deletion of ALKBH7 caused obesity and led to an increase in body weight in Mus musculus." (PMID 33292532, 2020). "Furthermore, the Alkbh7-/- mouse exhibits obesity due to defective fatty acid β-oxidation and an Alkbh7 mis-sense mutation (R191Q) has been linked to prostate cancer." (PMID 32795389, 2020). "ALKBH7 is a mitochondrial protein involved in programmed necrosis, fatty acid metabolism and obesity development." (PMID 35222541, 2022). "Moreover, ALKBH7 knockout mice exhibited an abnormally high level of body fat, suggesting a role for ALKBH7 in fat metabolism and obesity." (PMID 37007161, 2023).
prostate carcinoma (5 papers, 2017 to 2024). A carcinoma that arises from epithelial cells of the prostate gland. "A single-nucleotide polymorphism (SNP) of ALKBH7 was clarified as a new prostate cancer biomarker in 2017." (PMID 35620462, 2022). "Taken together, these results give important insights into a novel prostate-cancer related SNP and its impact on the structure and function of ALKBH7." (PMID 28231280, 2017). "Given the relation of some ALKBH family enzymes to prostate cancer, we have performed a targeted search for prostate cancer-related SNPs of ALKBH homologues using HyDn-SNP-S, followed by computational and experimental investigations related to a SNP of ALKBH7 resulting in a missense mutation." (PMID 28231280, 2017).
glioblastoma (2 papers, 2024). The most malignant astrocytic tumor (WHO grade IV). "In the present study, we observed higher expression of APNG in glioblastoma cells after indirect co‐culturing with TAAs via ALKBH7‐mediated crosstalk, and APNG expression was negatively correlated with the level of DNA damage repair marker γ‐H2AX." (PMID 38332576, 2024). "ALKBH7 exerted regulatory effects on apoptosis inhibition in APNG‐mediated TMZ resistance of glioblastoma cells, and ALKBH7 delivering via TAAs limited the cytotoxic efficacy of TMZ against glioblastoma cells in vitro." (PMID 38332576, 2024). "Colony formation ability of those two glioblastoma cells decreased after co‐culturing with si‐ALKBH7 TAAs upon TMZ exposure." (PMID 38332576, 2024). "Overall, these results demonstrated that ALKBH7 affected TMZ resistance of glioblastoma by regulating APNG expression." (PMID 38332576, 2024). "Our findings contributed to deeper understanding of the role of ALKBH7 in regulating APNG to promote TMZ resistance during crosstalk between glioblastoma cells and TAAs." (PMID 38332576, 2024). "The effect of TAAs‐derived ALKBH7 on TMZ resistance of glioblastoma in vivo was investigated as well." (PMID 38332576, 2024). "In summary, ALKBH7 was upregulated in GSCs‐exos educated TAAs and can mediate crosstalk with glioblastoma cells leading to upregulation of APNG, thus enhancing chemo‐resistance of glioblastoma." (PMID 38332576, 2024). "Two independent ALKBH7 siRNAs (si‐ALKBH7‐1, si‐ALKBH7‐2) were transfected into two glioblastoma cells, respectively." (PMID 38332576, 2024). "The results disclosed that the apoptosis rate of glioblastoma cells with addition of TAAs‐exos or oe‐ALKBH7‐exos decreased significantly, compared with NHAs‐exos or si‐ALKBH7 TAAs‐exos group." (PMID 38332576, 2024). "After co‐culturing with TAAs, the transfer of si‐ALKBH7 into glioblastoma cells resulted in reduced accumulation of γH2AX after TMZ administration." (PMID 38332576, 2024). "Subsequently, glioblastoma cells were co‐cultured with TAAs for 5 days, then transduced with ALKBH7 siRNAs." (PMID 38332576, 2024). "Collectively, our findings emphasized that aberrant activation of the ALKBH7 regulatory network facilitated glioblastoma chemo‐resistance through overexpression of APNG, leading to increased TMZ resistance." (PMID 38332576, 2024). "Compared with the si‐ALKBH7 group, the apoptosis rate of co‐cultured glioblastoma cells with si‐ALKBH7&APNG‐oe decreased significantly after supplementation of TMZ for 48 h." (PMID 38332576, 2024). "Stable knockdown of ALKBH7 in glioblastoma cells resulted in smaller xenografts (p < 0.01), which implied that ALKBH7 depletion in glioblastoma cells effectively restored the sensitivity of TMZ in vivo." (PMID 38332576, 2024). "Furthermore, our studies disclosed a novel mechanism that GSCs‐exos educated TAAs conferred TMZ resistance to glioblastoma cells via delivering ALKBH7 to upregulated APNG." (PMID 38332576, 2024). "It was further investigated whether APNG expression was required in the effect of ALKBH7‐induced TMZ resistance on glioblastoma cells." (PMID 38332576, 2024). "In addition, after co‐culturing with TAAs, transfer of si‐ALKBH7&APNG‐oe into glioblastoma cells resulted in reduced accumulation of γ‐H2AX after TMZ administration compared to the si‐ALKBH7 group." (PMID 38332576, 2024). "Declined transmission of ALKBH7 further indicated that ALKBH7 content of TAAs to transfer TMZ resistance to glioblastoma cells decreased obviously, which implied that ALKBH7 can regulate APNG expression, knocking‐down of ALKBH7 expression remarkably reduced APNG level." (PMID 38332576, 2024). "The ensuing analysis revealed a noteworthy positive correlation between the expression levels of ALKBH7 and APNG, which provided potential targets for further investigation into the underlying mechanisms driving glioblastoma progression and therapeutic responsiveness." (PMID 38332576, 2024).
glioblastoma (continued). "Furthermore, a concomitant increase in γ‐H2AX expression of glioblastoma cells can be observed after co‐culturing with si‐ALKBH7 TAAs." (PMID 38332576, 2024). "In addition, after addition of exosomes derived from NHAs, TAAs, si‐ALKBH7 TAAs or oe‐ALKBH7 TAAs, ALKBH7 expression level of glioblastoma cells with addition of TAAs‐exos or oe‐ALKBH7‐exos increased, compared to those with NHAs‐exos or si‐ALKBH7 TAAs‐exos group." (PMID 38332576, 2024). "The reciprocal regulatory relationship between ALKBH7 and APNG identified in the current study offered a valuable experimental basis for exploring new strategies focusing on ALKBH7‐dependent APNG expression against TMZ‐resistance of glioblastoma." (PMID 38332576, 2024). "TAAs had a high level of ALKBH7 expression, and TAAs‐derived secretory ALKBH7 can induce upregulation of APNG in glioblastoma cells, suggesting the role of ALKBH7 mediating on APNG upregulation during crosstalk between TAAs and glioblastoma cells to promote TMZ resistance." (PMID 38332576, 2024). "Noncontact co‐culture of glioblastoma cells (SNB19 or SF295, seeded in the bottom compartment) and TAAs, or si‐ALKBH7 TAAs (seeded in the top chamber) was conducted." (PMID 38332576, 2024).
hepatocellular carcinoma (2 papers, 2022 to 2024). A malignant tumor that arises from hepatocytes. "ALKBH7 expression is significantly elevated in hepatocellular carcinoma and negatively correlates with CD4+ cells, macrophages and neutrophils." (PMID 35222541, 2022).
ovarian serous carcinoma (2 papers, 2023 to 2024). "ALKBH7 was correlated with the pathological stage of ovarian serous carcinoma and positively correlated with the infiltration of CD8+ T cells, dendritic cells, and neutrophils." (PMID 37654657, 2023).
Alzheimer disease (1 paper, 2020). A progressive, neurodegenerative disease characterized by loss of function and death of nerve cells in several areas of the brain leading to loss of cognitive function such as memory and language. "The only other protein significantly upregulated in Alkbh7-/- was heme binding protein 1 (Hebp1), and notably a recent study found both GLO-1 and Hebp1 were upregulated in Alzheimer’s disease, suggesting these proteins may share a common upstream regulator." (PMID 32795389, 2020).
cerebellar degeneration (1 paper, 2017). Degeneration of the cerebellum. "Notably, the protection against alkylation-induced cerebellar degeneration is specific to ALKBH7-deficient male but not female mice." (PMID 28726787, 2017).
cervical cancer (1 paper, 2023). A primary or metastatic malignant neoplasm involving the cervix. "ALKBH7 is also known to be involved in cellular immunity and proliferation of the HeLa cervical cancer cell line." (PMID 37654657, 2023). "Among them, highly expressed ALKBH7 was associated with better prognosis and survival, was positively correlated with non-HPV infection, and was also significantly downregulated in cervical cancer." (PMID 37654657, 2023).
cervical clear cell carcinoma (1 paper, 2023). "Herein, we used comparative analysis to screen out genes with large differences in expression between HPV-negative and HPV-positive cervical clear cell carcinoma patients, including ALKBH7, MYCBP, MZF1, RNF207, RRS1, and TUSC2." (PMID 37654657, 2023).
gastric cancer (1 paper, 2024). A primary or metastatic malignant neoplasm involving the stomach. "Conversely, ALKBH2, ALKBH3, ALKBH5, ALKBH6, and ALKBH7 showed low expression in gastric cancer tissues." (PMID 38902235, 2024).
laryngeal squamous cell carcinoma (1 paper, 2024). A squamous cell carcinoma that arises from the larynx. "The Kaplan-Meier OS analysis showed that survival was worse in cancer patients with reduced ALKBH7 expression, especially in the laryngeal squamous cell carcinoma, suggesting that low ALKBH7 expression is associated with poor survival outcomes in HNSC." (PMID 39400540, 2024). "First, our study assessed the correlation between the mRNA and protein levels of ALKBH7 and the development and progression of laryngeal squamous cell carcinoma, a highly prevalent cancer in HNSC." (PMID 39400540, 2024). "Additionally, we investigated the effect of ALKBH7 expression on prognosis in different anatomic neoplasm subdivision of HNSC, finding that high expression of ALKBH7 was associated with a better prognosis in laryngeal squamous cell carcinoma compared to other types of HNSC." (PMID 39400540, 2024).
liver cancer (1 paper, 2022). An epithelial or non-epithelial malignant neoplasm that arises from the liver. "As liver cancer is considered an immunogenic tumor, the relationship between the expression of DOCK2, SCTR, TANC1, ALKBH7, FREM2, and GNG4 and the levels of immune cells and stromal cells was assessed." (PMID 35620462, 2022).
retinal degeneration (1 paper, 2017). Degeneration of the retina. "Although ALKBH7 contributes equally toward protecting against alkylation-induced retinal degeneration in both male and female mice, we have identified a sexually dimorphic response to alkylation-induced damage in the cerebellum." (PMID 28726787, 2017). "Interestingly, male WT mice exhibited the most severe retinal degeneration induced by MMS that was significantly reduced in male Alkbh7−/− mice." (PMID 28726787, 2017).
small cell lung carcinoma (1 paper, 2024). Small cell lung cancer (SCLC) is a highly aggressive malignant neoplasm, accounting for 10-15% of lung cancer cases, characterized byrapid growth, and early metastasis. "In the KEGG enrichment term, lowly expressed ALKBH7 was mainly correlated with inositol phosphate metabolism, small cell lung cancer, adheres junction, and dorsoventral axis formation pathways." (PMID 39400540, 2024).